ABCA4 (ATP binding cassette subfamily A member 4)
Diseases named in the same sentence as ABCA4 in open-access papers (continued):
Sharing a sentence is not in itself a finding about the gene and the disease.
Macular dystrophy (continued). "Furthermore, the study highlighted the importance of sequencing of PRPH2 and ABCA4 genes since in several patients both genotype and a reevaluation of the phenotype pointed towards an inherited macular dystrophy, rather than AMD." (PMID 36108770, 2022). "Because of these many confounders, incomplete penetrance, variable expressivity, unknown family, adoption, consanguinity, early deaths, missed or false diagnosis, the inheritance pattern alone is not sufficient to distinguish between ABCA4-, ELOVL4- and PRPH2-linked macular dystrophies." (PMID 34073554, 2021).
macular degeneration (24 papers, 2006 to 2026). Loss of vision in the central portion of the retina (macula), secondary to retinal degeneration. "ABCA4 is one of the most frequently mutated genes associated with IRDs and STGD1 is the most common inherited macular degeneration in working-aged individuals." (PMID 40269797, 2025). "STGD1 is the more common cause of macular degeneration in children and young adults related to mutations in the ABCA4 gene." (PMID 35629375, 2022). "Even in Spain, and in spite of its geographic proximity, Leu11Pro frequency is significantly lower (<1%) in macular degenerations associated with ABCA4 mutations." (PMID 19365591, 2009). "This group included rod specific genes Rbp3, Elovl4, and Abca4, the last two of which have been associated with macular degeneration in humans." (PMID 17044933, 2006). "For these reasons, we suggest that primary RPE degeneration phenotype with drusen-like deposits present in these Prpf31 mutant mice could be due to splicing defects in genes that could be associated with macular degenerative diseases such as ABCA4." (PMID 31892304, 2019). "Similarly in other macular degenerations such as those caused by ABCA4 mutations, the abnormal gene product is known to be expressed across all rod and cone photoreceptors yet the disease is initially and most severely expressed at or near the fovea centralis." (PMID 24599007, 2014). "RPGRIP, RANBP2, NPM1, PDE6D, and NPHP5 were selected on the basis of protein interaction with RPGR or RPGRIP1 as these two proteins independently cause photoreceptor degeneration when mutated; ABCA4 was selected as a control gene, and because of its association with macular degeneration and RP." (PMID 17653054, 2007). "Moreover, albino Abca4−/− mouse model of inherited macular degeneration exhibits progressive photoreceptor loss beginning at 8 months of age, whereas no photoreceptor death was observed up to 18 months of age in pigmented Abca4−/− mice." (PMID 36393836, 2022). "Mutations in the ABC transporter ABCA4 (ABC, subfamily A, member 4) are responsible for recessive Stargardt disease 1 (STGD1), a juvenile form of macular degeneration." (PMID 41654128, 2026). "Examining each patient individually, heterozygous c.4297G>A/p.Val1433Ile of the ABCA4 transmitted from the father was identified in a patient diagnosed with macular degeneration (Case ad5)." (PMID 38785568, 2024). "One case has only a single ABCA4 mutation, one has a variant of unknown significance in CBR1 and one sample has no demonstrable mutations in any gene with known association to retinal or macular degeneration." (PMID 22863181, 2012). "When ABCA4 is defective, N-ret-PE irreversibly forms a toxic, insoluble, bisretinoid known as A2PE which is deposited in retinal pigment epithelium (RPE) cells during the process of disc shedding and phagocytosis, eventually leading to cell death and macular degeneration." (PMID 24632595, 2014).
Stargardt disease type 1 (17 papers, 2016 to 2025). "STGD1 is a juvenile macular degeneration caused by mutations in the retina-specific ATP-binding cassette (ABC) transporter 4 (Abca4) gene." (PMID 39984833, 2025). "Biallelic ABCA4 variants impair the function of the ATP-binding cassette subfamily A member 4 protein (ABCA4) and are responsible for Stargardt disease type 1 (STGD1) and related retinopathies." (PMID 37555651, 2023). "The ATP-binding cassette transporter type A4 (ABCA4) gene is one of these genes and has been linked to Stargardt disease type 1 (STGD1), fundus flavimaculatus, cone–rod dystrophy (CRD), and pan-retinal CRD." (PMID 37779911, 2023). "Stargardt disease type 1 (STGD1) is caused by biallelic pathogenic variants in ABCA4." (PMID 39943985, 2025). "Stargardt disease type 1 (STGD1) is a progressive retinal disorder caused by bi-allelic variants in the ABCA4 gene." (PMID 39838063, 2025). "Stargardt disease type 1 (STGD1), the most common form of hereditary macular dystrophy, can be caused by biallelic combinations of over 2200 variants in the ABCA4 gene." (PMID 38182646, 2024). "In total, there were 11 unique P/LP variants in three genes related to three genetic diseases: COL7A1 AR Epidermolysis bullosa dystrophica, ABCA4 Stargardt disease type 1, and CFTR cystic fibrosis." (PMID 36635046, 2023). "Dysfunction of ABCA4 leads to the accumulation of cytotoxic products (lipofuscin) in the photoreceptors and retinal pigment epithelium and can manifest in different phenotypes such as Stargardt disease type 1 (STGD1), fundus flavimaculatus, cone–rod dystrophy (CRD), and pan-retinal CRD." (PMID 37779911, 2023). "Unfortunately, for autosomal recessive ABCA4-associated retinopathy (ABCA4-AR), the most frequent inherited macular dystrophy which includes Stargardt disease type 1 (STGD1), this is not very straightforward." (PMID 39943985, 2025). "Only one gene-disease pair occurred in both the non-ACMG SF and PF groups: ABCA4 Stargardt disease type 1 (one time as SF, two times as PF)." (PMID 36635046, 2023). "Only one gene-disease pair occurred in both groups, the non-ACMG SF and PF: ABCA4 Stargardt disease type 1 (one time as SF, two times as PF)." (PMID 36635046, 2023).
Leber congenital amaurosis (14 papers, 2011 to 2026). Leber congenital amaurosis (LCA) is a retinal dystrophy defined by blindness and responses to electrophysiological stimulation (Ganzfeld electroretinogram (ERG)) below threshold, associated with severe visual impairment within the first year of life. "Case 6a illustrates that a severe, early-onset ABCA4-RD can occasionally mimic Leber congenital amaurosis (LCA), and in this case particularly with LCA caused by CRB1 variants." (PMID 38066771, 2023). "For example, mutations in ABCA4, CRX, CERKL, PROM1, SEMA4A, GUCY2D can cause either CCRD, but also RP or Leber congenital amaurosis (LCA)." (PMID 26103963, 2015). "Other diseases, most notablyPRPH2- and ROM1-associated patterndystrophy and RDH12-associated Leber congenital amaurosis(LCA), have been reported to exhibit a similar manifestation although not asconsistent as in ABCA4-associated retinopathy." (PMID 32278709, 2020). "This individual was diagnosed with Leber congenital amaurosis at age 3.5 years, and at their last visit at age 8 years, fundus examination showed mild retinal pigmentary mottling and attenuated vessels, consistent with RPE65-associated retinopathy, with no signs of ABCA4-associated maculopathy." (PMID 38219857, 2024).
Usher syndrome (13 papers, 2013 to 2025). A syndromic diseae characterized by the association of sensorineural deafness (usually congenital) with retinitis pigmentosa and progressive vision loss. "Previous studies observed effect ratios ranging from 76% (16/21) of NCSS variants in genes associated with Usher syndrome, 94% (44/47) of variants in an ABCA4-specific study and four out of four NCSS variants in a study focusing on variants associated with IRD in general." (PMID 36362125, 2022). "Disruption of the ABCA4 gene was also concluded to be the cause of visual impairment in a single patient referred with Usher syndrome but is not expected to contribute to the clinical presentation of hearing loss." (PMID 27208204, 2016). "As a result, expanded capacity vectors can now accommodate genes such as CEP290, ABCA4, and MYO7A, genes responsible for LCA, SMD, and Type 1 Usher syndrome, respectively." (PMID 29326851, 2017). "Nonviral vectors developed through studies on vector capacity have increased the number of target genes, and genes such as CEP290 in LCA, ABCA4 in SMD, and MYO7A in Type 1 Usher syndrome are currently within capacity." (PMID 29326851, 2017). "Given that Usher syndrome type 1 typically presents with early-onset, progressive RP, it is possible that ABCA4-related changes are masked or have not yet manifested." (PMID 40269797, 2025).
Bull's eye maculopathy (12 papers, 2014 to 2026). Progressive maculopathy characterized by concentric regions of hyper- and hypopigmentation, with an initial foveal sparing and whose appearance is said to resemble the central target of a dart board. "In a similar study, the use of qAF was shownto be effective in differentiating ABCA4-associated retinopathyfrom non-ABCA4-associated retinopathy (masquerading)bull’s eye maculopathy phenotypes." (PMID 32278709, 2020). "While ABCA4-associated STGD (STGD1, OMIM #248200) is an autosomal recessive condition, there are two autosomal dominant MDs that have phenotypical features that can overlap with some of the presentations of STGD1 (including bull's-eye maculopathy)." (PMID 31704701, 2020). "The patient carrying Cys205Phe (P4) had a later age at presentation (36 years) and was diagnosed with ABCA4-RD in stage I, having a non-progressing bull's eye maculopathy without flecks." (PMID 39087934, 2024).
Atrophy (11 papers, 2015 to 2025). Any weakening or degeneration, especially through lack of use. "ABCA4 can also transportN‐11‐cis‐retinylidene‐phosphatidylethanolamine, the Schiff‐base adduct of11‐cis‐retinal; loss of function mutation cause a buildup of lipofuscin,atrophy of the central retina, and severe progressive loss in vision." (PMID 26650446, 2015). "While subretinal administration was generally tolerated, the observation that approximately one-quarter of participants developed increased RPE atrophy raises important safety concerns and highlights the need for further refinement of ABCA4 delivery approaches." (PMID 41440982, 2025). "Mutations in the ATP binding cassette subfamily A member 4 (ABCA4) gene are associated with STGD (OMIM: Entry—#248200—STARGARDT DISEASE 1) leading to bilateral loss of central vision, a delay in dark adaption, and an atrophy of the macula." (PMID 36857739, 2023). "Ophthalmoscopy and retinal imaging revealed features of ABCA4-related retinopathy including pronounced bilateral chorioretinal atrophy, pigmentary alterations as well as abnormally in- and decreased AF surrounding the area of atrophy." (PMID 32013026, 2020).
achromatopsia (9 papers, 2013 to 2024). Achromatopsia (ACHM) is a rare autosomal recessive retinal disorder characterized by color blindness, nystagmus, photophobia, and severely reduced visual acuity due to the absence or impairment of cone function. "Of 19 diseases, 10 had >10 participants: ABCA4 retinopathy; CNGB3- and CNGA3-associated achromatopsia; RPGR-associated disease; RPE65-associated disease; blue cone monochromacy (BCM); Bornholm eye disease (BED); TYR- and OCA2-associated oculocutaneous albinism; and GPR143-associated ocular albinism." (PMID 35704304, 2022). "Interestingly, we found that one of the control samples also carried additional pathogenic variants in ABCA4 gene and RPGRIP1 gene and this sample was from a patient who was diagnosed with Achromatopsia (RD13–08)." (PMID 28838317, 2017).
Blindness (8 papers, 2011 to 2025). Blindness is the condition of lacking visual perception defined as a profound reduction in visual perception. "The retina-specific ABCA transporter, ABCA4, is essential for vision, and its genetic variants are associated with a wide range of inherited retinal degenerative diseases, leading to blindness." (PMID 39222682, 2024). "All diseases associated with ABCA4 are progressive retinopathies accompanied by degeneration of photoreceptor cells that can lead to blindness." (PMID 35194496, 2022).
breast cancer (8 papers, 2009 to 2025). A primary or metastatic malignant neoplasm involving the breast. "Variation of ABCA4 was associated with therapy response in breast cancer." (PMID 36807122, 2023).
autosomal recessive cone rod dystrophy (6 papers, 2008 to 2023). autosomal cone rod dystrophy is an autosomally recessive inherited retinal dystrophy that belongs to the group of pigmentary retinopathies. "Seven genes reported to be associated with autosomal recessive cone-rod dystrophies (crd), ABCA4, RDH5, CORD8, CORD9, RPGRIP1, CRX and GUCY2D were therefore included in the study." (PMID 18593457, 2008). "The clinical manifestation of ABCA4-related retinopathy is variable, including autosomal recessive Stargardt’s disease (arSTGD), fundus flavimaculatus, autosomal recessive cone-rod dystrophy (arCRD) and autosomal RP." (PMID 28890726, 2017).
lung carcinoma (6 papers, 2011 to 2022). "ABCA4, ABCC1, and ABCC showed significant associations with lung cancer susceptibility (P-values<0.0005)." (PMID 23762359, 2013). "Our microarray analysis results and preliminary lung tissue array study demonstrated that the ABC gene signature, consisting of ABCA4 and ABCA8 together with ABCC3, can discriminate lung AC vs AT and be considering as a novel lung cancer diagnostic biomarker (not published)." (PMID 22369099, 2011).
autosomal recessive retinitis pigmentosa (5 papers, 2008 to 2015). Autosomal recessive retinitis pigmentosa (RP) is an autosomally recessive inherited retinal dystrophy leading to progressive loss of the photoreceptors and retinal pigment epithelium and resulting in blindness usually after several decades. "Compound heterozygous cases that included the p.Arg602Trp mutation of the ABCA4 gene have been described in early onset, autosomal recessive retinitis pigmentosa families." (PMID 24444108, 2014). "Biallelic mutations in ABCA4 are found in most patients with autosomal recessive STGD (arSTGD) as well as in some patients with autosomal recessive retinitis pigmentosa (arRP) and autosomal recessive cone-rod dystrophy (arCRD)." (PMID 18334942, 2008). "Mutations in the ABCA4 gene have been linked to several conditions such as autosomal recessive retinitis pigmentosa (arRP), autosomal recessive Stargardt disease (arSTGD), autosomal recessive cone-rod dystrophy (arCRD), bull’s eye maculopathy, and age-related macular degeneration." (PMID 24444108, 2014). "The photoreceptor cell-specific ATP-binding cassette transporter (ABCA4) gene is located on chromosome 1p21-p13 and has been implicated in up to 5% of autosomal recessive retinitis pigmentosa cases." (PMID 22131872, 2011). "Mutations in ABCA4 have been associated with autosomal recessive Stargardt disease (STGD), a few cases with autosomal recessive cone–rod dystrophy (arCRD) and autosomal recessive retinitis pigmentosa (arRP)." (PMID 19028736, 2009).
glioma (5 papers, 2016 to 2022). A benign or malignant brain and spinal cord tumor that arises from glial cells (astrocytes, oligodendrocytes, ependymal cells). "High DEGs in grade II gliomas included NNMT, MFAP5, APCDD1L-AS1, C7orf57, HP, SERPINA5, and LTF and some highly downregulated DEGs included ABCA4, PDE6A, GRP, RD3, and TMEM72." (PMID 33948562, 2021).
inherited macular dystrophy (5 papers, 2019 to 2025). "The most prevalent inherited macular dystrophy is STGD1, which is caused by abnormalities in the ATP-binding cassette transporter subfamily A4 (ABCA4) gene." (PMID 36359825, 2022).
night blindness (5 papers, 2017 to 2025). Inability to see clearly in dim light. "The presence of night blindness, typically unusual in young children with ABCA4-IRD, can also be attributed to the CACNA1F variant." (PMID 40269797, 2025). "Loss of function of ATP binding cassette subfamily a member 4 (ABCA4), which is retina specific and transports retinoids, is associated with both autosomal recessive Stargardt disease 1 and retinitis pigmentosa, a common inherited cause of nyctalopia (night blindness) and photoreceptor loss." (PMID 29321376, 2018). "We present herein five patients with the diagnosis of EOSRD related to ABCA4 with non-recordable ERG, night-blindness, and important visual impairment early in the first years of life." (PMID 29186038, 2017).
orofacial clefting (5 papers, 2016 to 2025). "In our study, several nonsynonymous variants in ABCA4 were specifically found in individuals with nonsyndromic orofacial clefts from a Taiwanese population." (PMID 27527345, 2016). "Nonsynonymous variants in MYH9 and ABCA4, which were detected in 6 and 5 individuals, respectively, were identified to be the most frequent risk loci in nonsyndromic orofacial clefts in the Taiwanese population." (PMID 27527345, 2016). "In Honduran and Colombian populations, ABCA4 is a candidate gene associated with nonsyndromic orofacial clefting." (PMID 27527345, 2016). "In contrast to our findings, neither rs560426 nor rs4147811 in ABCA4 was associated with orofacial cleft in a Nigerian population." (PMID 34769998, 2021). "Nonsynonymous variants in MYH9 and ABCA4 were identified to be the most frequent risk loci in nonsyndromic orofacial clefts in the Taiwanese population." (PMID 27527345, 2016). "For example, SNPs, such as the ones we identified, in the ABCA4 gene have previously been shown to be in enhancer regions which control ARHGAP29 expression and evidence suggests that it is ARHGAP29 not ABCA4 that plays a role in orofacial clefting." (PMID 41075272, 2025).
Tangier disease (5 papers, 2011 to 2022). "Screens for small molecule treatments have been instigated, including for Tangier disease (ABCA1), gout (ABCG2), Stargardt eye disease (ABCA4), progressive familial intrahepatic cholestasis type 2 (ABCB11), and congenital hyperinsulinemia." (PMID 30659068, 2019).
age related macular degeneration 2 (4 papers, 2018 to 2025). An age related macular degeneration conferred by variation in the ABCA4 gene on chromosome 1p22. "At the same time, heterozygous pathogenic variants in ABCA4 have also been reported in association with age-related macular degeneration type 2 (ARMD2), which typically manifests later in life (43–45 years)." (PMID 41465088, 2025). "ABCA4 age-related macular degeneration type 2 was most frequent among non-ACMG SFs." (PMID 36635046, 2023).
cleft lip (4 papers, 2015 to 2024). Congenital defect in the upper lip where the maxillary prominence fails to merge with the merged medial nasal prominences. "In addition to IRF6, v-maf musculoaponeurotic fibrosarcoma oncogene homolog B (MAFB) and intron 6 of the ATP-binding cassette subfamily A member 4 (ABCA4) also contribute to the risk of cleft lip and palate." (PMID 26322076, 2015). "The associations for the SNPs ABCA4 rs952499, SOX1-OT rs726455, and RORA rs877228 are of particular interest, as past research found associations between these genes and various craniofacial phenotypes, including cleft lip and/or palate." (PMID 38849772, 2024). "According to them, ARHGAP29 is a more plausible candidate for cleft lip and palate than ABCA4." (PMID 34769998, 2021). "Previous research showed that ABCA4 is associated with craniofacial skeletal variation among patients with skeletal malocclusion, and many studies have found associations between ABCA4 and SOX1-OT and cleft lip with or without cleft palate." (PMID 38849772, 2024).
congenital stationary night blindness (4 papers, 2020 to 2025). "Huynh and co-workers (2014) reported a case of a female patient with STGD1 and complete congenital stationary night blindness (CSNB1B), carrying biallelic ABCA4 variants (p.(Leu1201Arg) and p.(Arg2077Gly)) along with biallelic GRM6 gene variants (c.50_64del and c.1835_1837del)." (PMID 40269797, 2025). "However, the patient phenotype (congenital stationary night blindness—CSNB) did not fit this causative gene and the variants did not cosegregate with the phenotype in the family, leading to the conclusion that the ABCA4 was not the cause of disease in this case." (PMID 39062705, 2024).